CWC27 (CWC27 spliceosome associated cyclophilin)
Description:
As part of the spliceosome, plays a role in pre-mRNA splicing. Probable inactive PPIase with no peptidyl-prolyl cis-trans isomerase activity. As a component of the minor spliceosome, involved in the splicing of U12-type introns in pre-mRNAs (Probable).
Synonyms: SDCCAG10; NY-CO-10; SDCCAG-10; RPSKA
Tractability: Small molecule: a structure with a bound ligand is known. PROTAC: ubiquitination databases record sites on it; its protein half-life has been measured.
Gene: Protein-coding gene on chromosome 5 (64,766,368 to 65,102,412, forward strand). Ensembl gene ENSG00000153015.
Subcellular location: Nucleus
Subcellular location (Human Protein Atlas): Nucleoplasm
Pathways (Reactome):
Disease: Dengue Virus-Host Interactions
Metabolism of RNA: mRNA Splicing - Major Pathway
Gene Ontology:
Molecular function: peptidyl-prolyl cis-trans isomerase activity
Biological process: mRNA splicing, via spliceosome; protein folding
Cellular component: catalytic step 2 spliceosome; nucleoplasm; spliceosomal complex; U12-type catalytic step 2 spliceosome; U2-type precatalytic spliceosome; nucleus
Genetic constraint (gnomAD): Loss-of-function variants: 19 observed, 23.61 expected, observed/expected ratio (o/e) 0.8, 90% interval 0.56 to 1.18. The upper end of that interval is the gene's LOEUF score, 1.18, which puts it in group 5 of 6, group 1 being the genes least tolerant of losing a copy. Missense variants: 236 observed, 269.96 expected, observed/expected ratio (o/e) 0.87, 90% interval 0.79 to 0.97. Synonymous variants: 77 observed, 88.03 expected, observed/expected ratio (o/e) 0.87, 90% interval 0.73 to 1.06.
Gene-disease validity (ClinGen):
ClinGen rates the evidence that CWC27 causes each of these diseases.
metaphyseal chondrodysplasia-retinitis pigmentosa syndrome (autosomal recessive): Definitive.
Homologues: Orthologues: chimpanzee CWC27 (99% identical), macaque CWC27 (98% identical), rabbit CWC27 (94% identical), pig CWC27 (94% identical), dog CWC27 (91% identical), mouse Cwc27 (90% identical), rat Cwc27 (90% identical), tropical clawed frog cwc27 (74% identical), zebrafish cwc27 (71% identical), Drosophila melanogaster CG10907 (50% identical), Caenorhabditis elegans cyn-16 (44% identical). Paralogues in human: NKTR (30% identical), PPIG (25% identical), PPIL2 (22% identical), PPIL1 (17% identical), PPIL4 (17% identical), PPWD1 (16% identical), PPID (16% identical), PPIL3 (15% identical), PPIC (14% identical), PPIB (14% identical), PPIF (14% identical), PPIE (13% identical), and 10 more.
Diseases named in the same sentence as CWC27 in open-access papers:
CWC27 is named in the same sentence as 16 diseases in open-access papers, as found by Europe PMC text mining. Sharing a sentence is not in itself a finding about the gene and the disease. The quoted sentences say what the papers report.
retinal degeneration (4 papers, 2021 to 2022). Degeneration of the retina. "CWC27 was linked to ciliopathy-related symptoms such as retinal degeneration, as well as skeletal and neurological defects." (PMID 35885974, 2022). "There are less obvious putative links to potential global drivers of selection for other identified parallel genes CWC27, which is tentatively related to inflammation and retinal degeneration, and TENT2, possibly associated with post‐transcriptional gene regulation and epitranscriptomics." (PMID 35038768, 2022). "The most upregulated gene in the neuroretina of Gnat1rd17 mice, Cwc20, was a CWC22 spliceosome-associated protein that functions as the major partner of CWC27 (CWC27 spliceosome-associated cyclophilin), a splicing factor linked to retinal degeneration and other developmental defects." (PMID 35008877, 2021). "Importantly, those regions contained breed-specific genetic markers and candidate genes that are functionally related with pigmentation (e.g. PDE4D), UV protection (e.g. ERCC8), or retinal degeneration (e.g. CWC27, and CLUAP1)." (PMID 36288367, 2022).
Alzheimer disease (2 papers, 2024 to 2025). A progressive, neurodegenerative disease characterized by loss of function and death of nerve cells in several areas of the brain leading to loss of cognitive function such as memory and language. "CircRNA Cwc27 (CircCwc27) is a circular RNA that is highly expressed in the brain, particularly in the cortex and hippocampus, which are the brain regions most susceptible to damage in Alzheimer's disease (AD)." (PMID 38125754, 2024). "Silencing circRNA Cwc27 reduced neuropathological changes in Alzheimer’s disease and alleviated cognitive deficits." (PMID 41245147, 2025). "Furthermore, it was revealed that circRNA Cwc27 was upregulated in neurons and brains of APP/PS1 mice, as well as in temporal cortex and blood of Alzheimer’s disease patients." (PMID 41245147, 2025).
retinitis pigmentosa (2 papers, 2023). Retinitis pigmentosa (RP) is an inherited retinal dystrophy leading to progressive loss of the photoreceptors and retinal pigment epithelium and resulting in blindness usually after several decades. "Retinitis pigmentosa with or without skeletal abnormalities (RPSKA) is an autosomal recessive disorder caused by mutations in the CWC27 gene." (PMID 38134094, 2023). "Retinitis pigmentosa with or without skeletal anomalies (RPSKA) (OMIM: 250410) is an autosomal recessive genetic disease caused by mutations in the CWC27 gene." (PMID 38134094, 2023).
glaucoma (1 paper, 2016). Increased pressure in the eyeball due to obstruction of the outflow of aqueous humor. "Four genes (CARD10, CWC27, RERE, and USP37) were nominally enriched (uncorrected P < 0.05) in the glaucoma cohort." (PMID 27896285, 2016).
glioma (1 paper, 2022). A benign or malignant brain and spinal cord tumor that arises from glial cells (astrocytes, oligodendrocytes, ependymal cells). "In addition, we explored the proteins expressed by REEP6, LARP4B, CWC27, GOLGA2, ATP6AP1 and ERO1B in glioma patients through the HPA database, and REEP6, LARP4B, GOLGA2 and ATP6AP1 showed higher staining intensity in glioma than in normal brain tissue." (PMID 36552760, 2022).
CWC27 also shares sentences with these, for which no sentence is quoted: bladder cancer (3 papers); Bardet-Biedl syndrome (1); cancer (1); ciliopathy (1); connective tissue disorder (1); craniofacial microsomia (1); developmental delay (1); hearing loss (1); infection (1); keratoconus (1); retinopathy (1).